C1orf21 (chromosome 1 open reading frame 21)
Synonyms: PIG13
Tractability: PROTAC: ubiquitination databases record sites on it; its protein half-life has been measured.
Gene: Protein-coding gene on chromosome 1 (184,386,098 to 184,629,019, forward strand). Ensembl gene ENSG00000116667.
Subcellular location (Human Protein Atlas): Cytosol; Nucleoplasm
Gene Ontology:
Molecular function: protein binding
Genetic constraint (gnomAD): Loss-of-function variants: 2 observed, 18.05 expected, observed/expected ratio (o/e) 0.11, 90% interval 0.044 to 0.35. The upper end of that interval is the gene's LOEUF score, 0.35, which puts it in group 1 of 6, group 1 being the genes least tolerant of losing a copy. Missense variants: 104 observed, 148.25 expected, observed/expected ratio (o/e) 0.7, 90% interval 0.6 to 0.83. Synonymous variants: 41 observed, 48.67 expected, observed/expected ratio (o/e) 0.84, 90% interval 0.65 to 1.09.
Homologues: Orthologues: chimpanzee C1H1orf21 (100% identical), macaque C1H1orf21 (100% identical), dog C1orf21 (99% identical), guinea pig C1orf21 (97% identical), mouse 1700025G04Rik (97% identical), rat C13h1orf21 (97% identical), tropical clawed frog c4h1orf21 (77% identical), zebrafish zgc:92140 (63% identical), zebrafish zgc:55943 (55% identical), Drosophila melanogaster tow (32% identical), Caenorhabditis elegans R02E12.5 (20% identical).
Diseases named in the same sentence as C1orf21 in open-access papers:
C1orf21 is named in the same sentence as 2 diseases in open-access papers, as found by Europe PMC text mining. Sharing a sentence is not in itself a finding about the gene and the disease. The quoted sentences say what the papers report.
melanoma (1 paper, 2021). A malignant, usually aggressive tumor composed of atypical, neoplastic melanocytes. "These genes along with their activation values Eq for melanoma (MEL) are, GPNMB (MEL activation = 18.59), UBL3 (MEL activation = 1.39), AP1S2 (MEL activation = 1.28), RAB38 (MEL activation = 0.91), EDNRB (MEL activation = 0.55), JUN (MEL activation = 0.34), and C1orf21 (MEL activation = -0.13)." (PMID 34570764, 2021).
C1orf21 also shares sentences with these, for which no sentence is quoted: Graves disease (1 paper).